BNIP3 (BCL2 interacting protein 3)
Diseases named in the same sentence as BNIP3 in open-access papers (continued):
Sharing a sentence is not in itself a finding about the gene and the disease.
osteosarcoma (22 papers, 2020 to 2026). A usually aggressive malignant bone-forming mesenchymal neoplasm, predominantly affecting adolescents and young adults. "BNIP3, a key mitophagy receptor, regulates intracellular iron levels and is implicated in osteosarcoma ferroptosis." (PMID 41249141, 2025). "Differently, BNIP3-mediated mitophagy is associated with the cisplatin-resistance in osteosarcoma and ovarian cancer." (PMID 38514650, 2024). "Five ferroptosis-associated genes (MUC1, MAP3K5, LURAP1L, HMOX1, and BNIP3) correlated with the prognosis of osteosarcoma were screened for the construction of the risk score model." (PMID 36899330, 2023). "Migration experiments confirmed that as a risk gene, BNIP3 can enhance osteosarcoma cell invasiveness and promote metastasis." (PMID 37190333, 2023). "Considering the effect of GABARAP on mitophagy in osteosarcoma, we next explored the expression of several key mitophagy-associated genes, including BNIP3, PINK1, Parkin, LC3B, p62, and Beclin1, which were significantly downregulated in GABARAP knockdown cells." (PMID 41346635, 2025). "Our findings highlight BNIP3 as a hazardous gene in osteosarcoma, with important roles in immune evasion and prognosis, suggesting its potential as a therapeutic target." (PMID 41809731, 2026). "Then, we further assessed the prognostic value of GABARAP and BNIP3 in three independent osteosarcoma cohorts, TARGET-OS, GSE21257, and GSE32981, respectively." (PMID 41346635, 2025). "Similar effects were observed in U2OS osteosarcoma cells expressing tf-BNIP3 and Cas9, confirming that the effectors we identified are not strictly cell-type specific (Fig. EV2C)." (PMID 38177312, 2024). "Osteosarcoma cell migration significantly decreased following knockdown of BNIP3, while it was significantly enhanced following BNIP3 overexpression." (PMID 37190333, 2023). "The proliferation of osteosarcoma cells was significantly inhibited after knockdown of BNIP3, while overexpression of BNIP3 significantly increased the proliferation of osteosarcoma cells." (PMID 37190333, 2023). "We investigated the regulation of apoptosis in osteosarcoma cell line 143B by BNIP3 expression levels." (PMID 37190333, 2023). "Apoptosis and EdU experiments confirmed that BNIP3 can inhibit osteosarcoma cell apoptosis and promote proliferation." (PMID 37190333, 2023). "Box plots and ROC curves proved that BNIP3 had good performance in osteosarcoma metastasis prediction." (PMID 37190333, 2023). "BNIP3 was found to play an essential role in osteosarcoma metastasis and progression and was verified by apoptosis, proliferation, and migration experiments." (PMID 37190333, 2023). "MAP3K5, LURAP1L, HMOX1 and BNIP3 expression levels were markedly decreased in the osteosarcoma cells compared with the normal human osteoblast hFOB1.19 cells, they are negatively related with the riskscore." (PMID 36899330, 2023). "Generally, the model had good prognostic value, and the role played by the BNIP3 gene in osteosarcoma occurrence and development was verified experimentally." (PMID 37190333, 2023). "ZnO NPs can inhibit osteosarcoma metastasis by degrading β-catenin in the HIF-1 α/BNIP3/LC3B-mediated mitophagy pathway." (PMID 37197432, 2023). "The results demonstrated that knockdown of BNIP3 significantly elevated the apoptosis rate of osteosarcoma cells, while overexpression of BNIP3 significantly decreased the apoptosis rate of osteosarcoma cells." (PMID 37190333, 2023). "In conclusion, the experimental results confirmed that the expression level of BNIP3 played an apoptosis-regulating role in osteosarcoma cell line 143B." (PMID 37190333, 2023). "BNIP3 is a unique pro-apoptotic protein with ACAA2 as a functional binding partner in human osteosarcoma U-2OS cells." (PMID 36899330, 2023).
osteosarcoma (continued). "All of these results suggested that BNIP3 has the potential to be a therapeutic target for osteosarcoma, with implications for clinical treatment and future research in osteosarcoma." (PMID 37190333, 2023). "Three key genes were studied to varying degrees, and BNIP3 was found to play an essential role in osteosarcoma metastasis and progression, verified by apoptosis, proliferation, and migration experiments." (PMID 37190333, 2023). "Cell proliferation assay showed that BNIP3 knockdown prominently attenuate the proliferation of osteosarcoma cells." (PMID 36578780, 2022). "Cell migration analysis further demonstrated that BNIP3 knockdown significantly decreased the migration of osteosarcoma cells." (PMID 36578780, 2022). "BNIP3 knockdown efficacy was confirmed by RT-PCR and western blot in Saos-2 and 143B osteosarcoma cells." (PMID 36578780, 2022). "Our in vitro models confirmed that BNIP3 knockdown significantly inhibited the proliferation and migration ability of osteosarcoma cells." (PMID 36578780, 2022). "A total of 46 genes showed an obvious relationship with the OS of osteosarcoma using a p value of less than 0.05 as the selection criteria, of which MYC (HR = 1.5, 95% CI: 1.1−2.2, p = 0.024) and BNIP3 (HR = 1.5, 95% CI: 1.1−2, p = 0.0073) were risk genes." (PMID 34335109, 2021). "The human osteosarcoma cell line U2OS also exhibited an increase in BNIP3 expression in response to IGF-1." (PMID 31936236, 2020). "Oxidative stress was also reported to contribute to baicalein-induced BNIP3 upregulation in human osteosarcoma cells." (PMID 32801360, 2020). "In a recent study, baicalein has been shown to inhibit the proliferation of MG-63 osteosarcoma cells and induce apoptosis through the expression of ROS-induced BNIP3." (PMID 32283909, 2020). "Finally, we verified the effect of BNIP3 on apoptosis, proliferation, and migration of osteosarcoma cells through experiments." (PMID 37190333, 2023). "In particular, the potential impact of BNIP3 in osteosarcoma was further explored." (PMID 37190333, 2023). "Our overall data indicate that by reverting the excess mitochondrial autophagy we could curtail the resistance to CDDP observed in ovarian cancer and osteosarcoma, and that BNIP3 could be a potential target useful to overcome the resistance phenomena." (PMID 35459212, 2022). "By inhibiting BNIP3-mediated mitophagy, the resistance to cisplatin observed in osteosarcoma could be reduced." (PMID 36578780, 2022). "BNIP3 overexpression could induce the apoptosis of osteosarcoma cells, and BNIP3 inhibition plays a suppressive role in osteosarcoma cells apoptosis." (PMID 34335109, 2021). "In addition, BMAL1 is able to bind to the promoter region of Bnip3 in osteosarcoma according to ChIP-seq analysis." (PMID 32277346, 2020). "qRT-PCR showed MYC, BNIP3, IGFBP5, and SPP1 substantially exhibited a trend of high expression in osteosarcoma cells." (PMID 41282023, 2025). "Further correlation analysis found BNIP3 to have a significantly positive correlation with MYC, NELL1, SAR1A, PLOD2, and other genes proven to promote osteosarcoma metastasis." (PMID 37190333, 2023). "The expression of BNIP3, SLC38A5, CKMT2, CXCL11, SLC5A3, S100A3, and PGM1 genes was verified in osteosarcoma cells (Saos-2 and 143B) and normal osteoblasts (hFOB1.19)." (PMID 36578780, 2022). "Our study identifies inhibition of BNIP3-driven mitophagy as a potential therapeutic strategy to counteract CDDP resistance in ovarian carcinoma and osteosarcoma." (PMID 35459212, 2022).
hepatocellular carcinoma (21 papers, 2015 to 2026). A malignant tumor that arises from hepatocytes. "BNIP3 inhibition in triple-negative breast cancer enhanced ROS-mediated mitophagy, promoting metastasis, whereas BNIP3 overexpression in hepatocellular carcinoma induced a greater degree of mitophagy, suppressing metastasis." (PMID 40361329, 2025). "FOXO3 impaired PINK1 protein stability by driving BNIP3 transcriptional repression in hepatocellular carcinoma." (PMID 36823640, 2023). "It contributed to not only doxorubicin-induced protective autophagy in hepatocellular carcinoma cells but also BNIP3 upregulation triggered by tunicamycin in cardiomyocytes." (PMID 33879840, 2021). "For example, Verticillin A induced BNIP3 expression in human colon carcinoma, and hepatoma has been reported to correlate with apoptosis." (PMID 33795637, 2021). "Previous studies have shown that ConA can induce the autophagic cell death of hepatoma cells in a BNIP-3-mediated manner." (PMID 26633714, 2015). "The increased MIF expression and secretion lead to autophagy through BNIP3 expression and LC3 conversion, which eventually causes hepatoma cell death." (PMID 26633714, 2015). "Through a comparative analysis of gene expression data from hepatocellular carcinoma samples with high vs. low EMP2 expression, we identified 28 genes associated with autophagy, such as IGFBP2 and BNIP3, suggesting a potential linkage between EMP2 and autophagy in liver cancer." (PMID 39866225, 2025). "The relevant results showed that increasing in the expression of BNIP3 following the treatment of hepatoma cells with concanavalin A inhibited the expression of Bcl‐2/Bcl‐2‐associated X protein ratio, resulting in mitochondrial dysfunction and the activation of caspase‐dependent apoptosis." (PMID 35243817, 2022). "Significant up-regulation of BNIP3 was induced by galectin-1 in hepatoma cells." (PMID 26859293, 2016). "In the liver, an overexpression of BNIP3 induces mitophagy disorder and apoptosis, promoting the development of hepatocellular carcinoma (HCC)." (PMID 38540059, 2024). "Hence we investigated whether soluble galectin-1 is able to induce the up-regulation of BNIP3 in hepatoma cells." (PMID 26859293, 2016). "Recent studies showed that GANT61 induced autophagic death in hepatocellular carcinoma (HCC) cells through upregulation of Bnip3." (PMID 25544756, 2015). "Therefore, we examined whether STAT3 and BNIP3 are involved in the ConA-induced autophagy of hepatoma cells." (PMID 26633714, 2015). "To further understand the sequential events induced by ConA-stimulated hepatoma cells, we used Stattic (STAT3 activation inhibitor) and found that it suppressed STAT3 phosphorylation, BNIP3 induction and LC3-II conversion." (PMID 26633714, 2015). "Furthermore, the detachment of hepatocellular carcinoma cells from the ECM allows anoikis escape through autophagy activation driven by destabilization of the mTORC1 complex and upregulation of BNIP3 (BCL2 Interacting Protein 3) via the ERK/HIF-1α pathway." (PMID 35884904, 2022). "Indeed, treating hepatoma cells with recombinant human MIF (rMIF) directly induced BNIP3 expression but not STAT3 phosphorylation, which were activated by ConA." (PMID 26633714, 2015).
glioblastoma (19 papers, 2009 to 2026). The most malignant astrocytic tumor (WHO grade IV). "In malignant glioblastoma cells, BNIP3 expression increases under ceramide induction, further activating mitochondrial autophagy and leading to cancer cell death." (PMID 39763653, 2024). "In agreement with our results, a study previously demonstrated the up-regulation of BNIP3 under hypoxic conditions in glioblastoma." (PMID 35200106, 2022). "Previous studies show that STAT3, as a transcription factor, promotes the expression of BNIP3 in concanavalin a-induced hepatitis and glioblastoma cells." (PMID 36207761, 2022). "In particular, in a model of glioblastoma, a reduction in α-tubulin has been observed to induce a downregulation of BNIP3 and NIX, with consequent inhibition of mitophagy." (PMID 34830966, 2021). "In particular, in a model of glioblastoma, the α-tubulin decrease—due to genetic alteration or pharmacological treatment—induced a downregulation of BNIP3 and NIX, and inhibited the selective mitophagic removal of mitochondria." (PMID 34830966, 2021). "We previously found that BNIP3 is localized to the nucleus in the majority of glioblastoma (GBM) tumors and in a subset of normal astrocytes." (PMID 30307949, 2018). "Bnip3 was also shown to confer survival signals in glioblastoma tumor cells by suppressing transcription of the apoptosis-inducing factor and death receptor 5 genes." (PMID 26317696, 2015). "For example, in glioblastomas, BNIP3 has recently been localized to the nucleus, where it binds to the Aif gene promoter and represses its expression, thereby inhibiting AIF-mediated cell death." (PMID 23646141, 2013). "The inverse relationship between BNIP3 and PGK1 was unexpected, and together with the minimal associations seen between several other proteins, suggests a multi-level regulatory system of the hypoxic pathway in glioblastoma." (PMID 35419292, 2022). "In glioblastoma and non-small lung carcinomas Bnip3 protein is sequestered in the nuclei where it may actually block apoptosis by suppressing transcription of the apoptosis-inducing factor (AIF) and death receptor 5 (DR5) genes." (PMID 24811485, 2014). "Another mechanism of mediation of BNIP3 activity may be intranuclear sequestration of BNIP3 protein, that has been reported in glial cells of the normal brain and in glioblastoma multiforme." (PMID 19505343, 2009). "In response to hypoxia, all three glioblastoma cell lines showed a robust stabilization of HIF-1α and an increase in BNIP3 protein, with T98G and U87MG also exhibiting an increase in CA-IX protein." (PMID 40123902, 2025). "For instance, in glioblastoma tumor cells, despite increased BNIP3 expression in hypoxic regions, its localization is not in mitochondria or the cytoplasm but in the nucleus." (PMID 39763653, 2024). "BNIP3 actually promotes neuronal cell survival, thus it is not surprising that its expression is neuroprotective in stroke but detrimental in glioblastoma." (PMID 38030595, 2024).
prostate carcinoma (18 papers, 2009 to 2025). A carcinoma that arises from epithelial cells of the prostate gland. "The transcription factor Sp3 regulates BNIP3 to inhibit the proliferation of prostate cancer cells and cause apoptosis." (PMID 34853602, 2021). "In non-small cell lung carcinoma, high levels of Bnip3 expression are associated with poor clinical outcome and in prostate cancer Bnip3 expression strongly correlates with the cancer stage or “Gleason” score." (PMID 24811485, 2014). "BNIP3, being a proapoptotic gene, has exhibited potential as a universal cancer suppressor in several types of cancer, such as prostate cancer, esophageal squamous cell carcinoma, and pancreatic cancer." (PMID 40028033, 2025). "It is found by Chen that miR-145 inhibits the proliferation of prostate cancer cells and promotes apoptosis by targeting the expression of BNIP3 protein, thereby inhibiting tumor progression." (PMID 35783530, 2022). "In prostate cancer, hypomehtylation of BNIP3 and hypermethylation of both EC-SOD and RASSF1A were observed." (PMID 34136546, 2021). "For example, the member of the basic helix-loop-helix/PAS (bHLH/PAS) transcription factors SIM2s, has been shown to attenuate BNIP3 hypoxic induction via cross-talk with HIF-1α on the HRE in prostate cancer cells." (PMID 28968982, 2017). "In prostate cancer, there was a significant correlation between cytoplasmic BNIP3 expression and Gleason score, age, and Glut1, and between nuclear BNIP3 expression and HIF-1α." (PMID 19505343, 2009). "Similarly, in prostate cancer, a significant correlation between cytoplasmic BNIP3 expression and unfavorable patient outcomes was found." (PMID 33207677, 2020). "The proposed mechanism for these findings is as follows; in prostate cancer, androgen is bound to AR, which activates HIF-1α through a cascade of several protein kinase systems, continuously increasing expression of the HIF-1α-related gene, one of which is BNIP3." (PMID 25140630, 2014).
colon carcinoma (16 papers, 2012 to 2025). "Cisplatin cytotoxicity increased with ascending BNIP3 level in several clonal variants of human colon carcinoma cell line HT29, and up‐regulation of BNIP3 in HT29 significantly increased its cisplatin sensitivity." (PMID 32412667, 2020). "The downregulation of BNIP3 accelerates colon cancer cell growth and reduces sensitivity to chemotherapy, potentially related to BNIP3’s cellular localization." (PMID 39763653, 2024). "BNIP3 downregulation accelerated the growth of colon cancer cells and weakened its sensitivity to chemotherapy." (PMID 36200262, 2022). "Up‐regulation of BNIP3 in colon carcinoma increased both spontaneous apoptosis and cisplatin‐induced apoptosis." (PMID 32412667, 2020). "BNIP3 silencing caused by promoter methylation and histone acetylation is associated with chemotherapy resistance and worse survival, and BNIP3 restoration enhances chemosensitivity and promotes tumor cell apoptosis in gastric and colon cancer." (PMID 29632473, 2018). "We reported for the first time that HSP90 inhibition intensely increased oxidative stress and endoplasmic reticulum stress through downregulating PINK1 and upregulating BNIP3 in colon cancer cells, subsequently reduced colon cancer cells survival and increased its apoptosis." (PMID 39921807, 2025). "Targeting HSP90 in colon cancer cells disrupts their survival by decreasing PINK1 and increasing BNIP3, which activates oxidative and endoplasmic reticulum stress, ultimately triggering apoptosis." (PMID 39921807, 2025). "However, in primary colon cancer, methylated BNIP3 does not exhibit high expression but rather shows a downregulated trend, and this downregulation is associated with abnormal methylation mediated by DNA methyltransferase 3β (DNMT3β) and DNA methyltransferase 1 (DNMT1)." (PMID 39763653, 2024).